ZBTB4 (zinc finger and BTB domain containing 4)
Description:
Transcriptional repressor with bimodal DNA-binding specificity. Represses transcription in a methyl-CpG-dependent manner. Binds with a higher affinity to methylated CpG dinucleotides in the consensus sequence 5'-CGCG-3' but can also bind to the non-methylated consensus sequence 5'-CTGCNA-3' also known as the consensus kaiso binding site (KBS). Can also bind specifically to a single methyl-CpG pair and can bind hemimethylated DNA but with a lower affinity compared to methylated DNA. Plays a role in postnatal myogenesis, may be involved in the regulation of satellite cells self-renewal (By similarity).
Synonyms: KAISO-L1; KIAA1538; ZNF903
Tractability: PROTAC: UniProt records ubiquitination sites on it; its protein half-life has been measured.
Gene: Protein-coding gene on chromosome 17 (7,459,366 to 7,484,263, reverse strand). Ensembl gene ENSG00000174282.
Subcellular location: Nucleus; Chromosome
Subcellular location (Human Protein Atlas): Nuclear bodies; Cytosol; Nucleoplasm
Gene Ontology:
Molecular function: DNA-binding transcription repressor activity, RNA polymerase II-specific; methyl-CpG binding; methyl-CpNpG binding; protein binding; protein homodimerization activity; protein kinase binding; RNA polymerase II transcription regulatory region sequence-specific DNA binding; sequence-specific DNA binding; DNA-binding transcription factor activity, RNA polymerase II-specific; RNA polymerase II cis-regulatory region sequence-specific DNA binding
Biological process: DNA damage response; negative regulation of DNA-templated transcription; negative regulation of transcription by RNA polymerase II; regulation of DNA-templated transcription
Cellular component: chromosome; nuclear body; nucleoplasm; nucleus
Genetic constraint (gnomAD): Loss-of-function variants: 14 observed, 56.83 expected, observed/expected ratio (o/e) 0.25, 90% interval 0.16 to 0.38. The upper end of that interval is the gene's LOEUF score, 0.38, which puts it in group 1 of 6, group 1 being the genes least tolerant of losing a copy. Missense variants: 1,198 observed, 1,368.5 expected, observed/expected ratio (o/e) 0.88, 90% interval 0.83 to 0.92. Synonymous variants: 587 observed, 569.07 expected, observed/expected ratio (o/e) 1.03, 90% interval 0.96 to 1.1.
Homologues: Orthologues: chimpanzee ZBTB4 (99% identical), macaque ZBTB4 (98% identical), dog ZBTB4 (90% identical), rabbit ZBTB4 (90% identical), guinea pig ZBTB4 (89% identical), rat Zbtb4 (85% identical), mouse Zbtb4 (85% identical), zebrafish zbtb4 (34% identical), Caenorhabditis elegans spr-3 (9% identical), Caenorhabditis elegans unc-98 (6% identical), Caenorhabditis elegans T22C8.3 (4% identical), Caenorhabditis elegans T22C8.4 (3% identical). Paralogues in human: ZBTB38 (25% identical), ZNF438 (10% identical).
Diseases named in the same sentence as ZBTB4 in open-access papers:
ZBTB4 is named in the same sentence as 31 diseases in open-access papers, as found by Europe PMC text mining. Sharing a sentence is not in itself a finding about the gene and the disease. The quoted sentences say what the papers report.
breast carcinoma (12 papers, 2011 to 2023). "ZBTB4 expression level is de-regulated in many cancers, such as prostate cancer, breast cancer, and lung cancer." (PMID 36538280, 2023). "Several studies have shown that ZBTB4 is downregulated in multiple tumor types, such as breast cancer, Ewing sarcoma, and colorectal cancer." (PMID 36276976, 2022). "In breast cancer cells, ZBTB4 transcriptionally suppresses the expression of EZH2 and inhibits the growth of cancer cells." (PMID 34047477, 2021). "In breast cancer, ZBTB4 can inhibit oncogene transcriptional activity, and its overexpression suppresses the growth and migration of cancer cells." (PMID 34047477, 2021). "The expression of ZBTB4 is downregulated in colon cancer, gastric cancer, retinoblastoma, Ewing sarcoma, breast cancer and prostate cancer, suggesting that ZBTB4 may have the potential to inhibit tumor development." (PMID 36949454, 2023). "Interestingly, ZBTB4 is known to act as a tumor suppressor in various types of cancers (prostate cancer; glioma; colorectal cancer; breast cancer; Ewing sarcoma), but more importantly, it is being investigated as a promissory anti-cancer druggable target." (PMID 36358698, 2022). "Suppression of miR-17 and miR-20a could inhibit growth and invasion of breast cancer cells via upregulation of tumor suppressor ZBTB4." (PMID 21980462, 2011). "Additionally, ZBTB4 is significantly downregulated in breast cancer tissues with longer 3′UTRs." (PMID 36358727, 2022). "A known repressor of transcription, zinc finger and BTB domain containing 4 (ZBTB4), suppresses the pathogenesis of many malignant tumors, such as prostate cancer, breast cancer, lung cancer, and Ewing sarcoma." (PMID 36538280, 2023). "Recently, HMG box-containing protein 1 (HBP1) and zinc-finger and BTB domain containing 4 (ZBTB4) were reported to be targets of miR-17-92 and to be correlated with the prognosis in breast cancer." (PMID 22952885, 2012).
prostate carcinoma (7 papers, 2015 to 2023). A carcinoma that arises from epithelial cells of the prostate gland. "Downregulation of ZBTB4 has been found in several common malignancies that include neuroblastoma, breast and prostate cancer." (PMID 31245293, 2019). "Similarly, ZBTB4 can transcriptionally inhibit specific protein transcription factors (Sp1, Sp3, and Sp4), thereby inhibiting the proliferation of prostate cancer cells and promoting cell apoptosis." (PMID 34047477, 2021). "ZBTB38 paralogs, ZBTB4 and ZBTB33/KAISO, are also implicated in the progression of prostate cancer." (PMID 32365491, 2020). "Elevated levels of ZBTB4 also correlated with longer survival of prostate cancer patients." (PMID 31245293, 2019). "We confirm alterations in six genes previously associated with prostate cancer (MAP3K7, MELK, RCBTB2, ELAC2, TPD52, ZBTB4), and also identify 94 genes not previously linked to prostate cancer progression that would not have been detected using either transcript or copy number data alone." (PMID 26501111, 2015).
colon carcinoma (5 papers, 2019 to 2023). "We performed ChIPseq using HCT116 colon carcinoma cells, identifying ~850 putative target genes associated with metabolism (e.g., Prdx5, Mdh1, Ahcy), transcription (Taf12, Tet2, histones), malignancy (Met, Blcap, Rras, Jag1, Gsk3a) and mitotic stability (Zbtb4)." (PMID 31059499, 2019). "Studies have shown that the expression of ZBTB4 in colon cancer tissues is significantly reduced, and increased ZBTB4 expression significantly prolongs the survival of patients." (PMID 34047477, 2021). "Moreover, in colon cancer cells where curcumin induces reactive oxygen species (ROS), curcumin was found to down-regulate microRNAs miR-27a, miR-20a, and miR-17-5p and regulate transcriptional repressors ZBTB10 and ZBTB4." (PMID 36499286, 2022).
Ewing sarcoma (5 papers, 2021 to 2023). A small round cell tumor that lacks morphologic, immunohistochemical, and electron microscopic evidence of neuroectodermal differentiation. "ZBTB4 overexpression inhibits cancer cell proliferation and induces cell cycle arrest at G1 phase as well as apoptosis in Ewing’s sarcoma." (PMID 34484284, 2021).
colorectal cancer (4 papers, 2013 to 2022). A primary or metastatic malignant neoplasm that affects the colon or rectum. "In colorectal cancer, patients with a high ZBTB4 expression have a better prognosis." (PMID 34671397, 2021).
glioma (4 papers, 2021 to 2024). A benign or malignant brain and spinal cord tumor that arises from glial cells (astrocytes, oligodendrocytes, ependymal cells). "Finally, our in vivo study revealed that MSI2 knockdown, SNORD12B knockdown, or ZBTB4 overexpression suppressed xenograft glioma tumor growth and was associated with prolonged survival." (PMID 34047477, 2021). "Next, we performed Western blot to observe the expression levels of ZBTB4 protein in NBTs, glioma tissues, NHAs, and GBM cells." (PMID 34047477, 2021). "Compared with that in NBTs, the expression of ZBTB4 protein was significantly lower in different grades of glioma tissues, and the magnitude of the downregulation increased with increasing pathological grade." (PMID 34047477, 2021). "MSI2 and SNORD12B expression was significantly increased and ZBTB4 expression was decreased in glioma tissues and cells." (PMID 34047477, 2021). "The present study revealed the oncogenic nature of MSI2 and SNORD12B and the antioncogenic role of ZBTB4 in glioma." (PMID 34047477, 2021). "ZBTB4 expression was downregulated in gliomas compared with that in NBTs." (PMID 34047477, 2021). "The glioma samples with patterns A and C showed high expression of ZBTB4 and NTHL, respectively, whereas, glioma samples with pattern B showed high expression of most DNA methylation regulators." (PMID 36152044, 2022). "ZBTB4 bind to the HK2 and ACLY promoter regions and inhibit their transcription, thereby impairing glycolipid metabolism and proliferation of glioma cells." (PMID 34047477, 2021). "Further, mice injected with a combination of the three showed minimal xenograft glioma volume and the longest survival time compared with those in the MSI2 knockdown, SNORD12B knockdown, or ZBTB4 overexpression group." (PMID 34047477, 2021). "Thus, the MSI2/SNORD12B/FIP1L1/ZBTB4 positive feedback loop plays a crucial role in regulating the glycolipid metabolism of GBM cells and provides a potential drug target for glioma treatment." (PMID 34047477, 2021).
gastric cancer (3 papers, 2013 to 2023). A primary or metastatic malignant neoplasm involving the stomach. "ZBTB4 expression in gastric cancer cells is markedly downregulated, and overexpression of ZBTB4 suppresses tumor cell growth." (PMID 34047477, 2021).
lung carcinoma (3 papers, 2022 to 2023). "Previous studies reported that ZBTB4 had cancer suppressive effects in humans and the expression was decreased in various cancers, including breast cancer, lung cancer, gastric cancer, and so on." (PMID 35774226, 2022). "M6A modification of ZBTB4 mediated by EZH2 is involved in CS-induced epithelial–mesenchymal transition (EMT) and lung cancer." (PMID 35774226, 2022).
bladder cancer (1 paper, 2012). "Moreover, celastrol also downregulates miR-20a and other miR paralogs with the same seed sequence in bladder cancer cells and this is accompanied by induction of ZBTB4." (PMID 23194063, 2012).
colitis (1 paper, 2026). Inflammation of the colon. "Here, we found that ZBTB4 deficiency exacerbates dextran sulfate sodium (DSS)-induced colitis in C57BL/6J male mice." (PMID 42193937, 2026). "NF-κB inhibition by JSH-23 alleviated the effect of ZBTB4 deficiency on DSS-induced colitis." (PMID 42193937, 2026).
diabetes (1 paper, 2022). "It has been documented that ZBTB4 is involved in the regulation of diabetes-related complications." (PMID 36276976, 2022).
pancreatic cancer (1 paper, 2023). "We are also concerned that the pan-cancer data identified a deletion of ZBTB4 expression in pancreatic cancer, which was also significantly associated with immune infiltration in pancreatic cancer tissues." (PMID 36949454, 2023). "According to our results, ZBTB4 is present in pancreatic cancer with aberrant expression and is associated with an altered immune microenvironment." (PMID 36949454, 2023). "We found that the level of ZBTB4 in peripheral blood had good diagnostic performance for pancreatic cancer." (PMID 36949454, 2023). "ZBTB4 had good diagnostic performance for pancreatic cancer in the clinic, and ZBTB4 protein expression was lost in pancreatic cancer tumor tissues." (PMID 36949454, 2023). "This suggests that pancreatic cancer has the same deficiency of ZBTB4 expression as other cancers." (PMID 36949454, 2023). "Immunohistochemical staining of tissue microarrays from pancreatic cancer also clarified that there was a low expression of ZBTB4 protein in pancreatic cancer tumor tissues." (PMID 36949454, 2023). "Next, we retrieved the Gene Expression Omnibus database expression datasets of ZBTB4 and investigated ZBTB4 expression and clinical significance in pancreatic cancer by immunohistochemical staining experiments." (PMID 36949454, 2023). "Cell experiments revealed that overexpression of ZBTB4 inhibited the proliferation, migration and invasion of pancreatic cancer cells, while silencing ZBTB4 showed the opposite effect." (PMID 36949454, 2023). "This was investigated using mRNA results from peripheral blood, which showed that ZBTB4 mRNA expression was remarkably reduced in the peripheral blood of pancreatic cancer patients relative to that in healthy individuals." (PMID 36949454, 2023). "In this manuscript, we show that ZBTB4 is a promising marker for cancer immunotherapy and cancer prognosis and has the potential to influence pancreatic cancer progression." (PMID 36949454, 2023). "We show that ZBTB4 is a promising marker for cancer immunotherapy and cancer prognosis and has the potential to influence pancreatic cancer progression." (PMID 36949454, 2023). "The Kaplan–Meier method was used to evaluate the prognostic significance of ZBTB4 in pancreatic cancer." (PMID 36949454, 2023). "Here, we focused on the clinical role played by ZBTB4 in pancreatic cancer by searching the GSE125158 dataset in the GEO database." (PMID 36949454, 2023). "We also show that the expression of ZBTB4 is downregulated in pancreatic cancer cell lines and can inhibit their development." (PMID 36949454, 2023). "Both RT-PCR and western blot results confirmed the low level of ZBTB4 in pancreatic cancer cell lines." (PMID 36949454, 2023). "Importantly, we verified the expression of ZBTB4 in clinical specimens of pancreatic cancer by immunohistochemistry and verified the expression of ZBTB4 in pancreatic cancer cell lines in experiments to explore its biological functions." (PMID 36949454, 2023). "This makes it interesting to understand the role that ZBTB4 plays in pancreatic cancer." (PMID 36949454, 2023). "We also partially investigated the role of ZBTB4 in pancreatic cancer." (PMID 36949454, 2023). "Finally, cell experiments were performed to investigate changes in pancreatic cancer cell proliferation, migration and invasion following overexpression and knockdown of ZBTB4." (PMID 36949454, 2023). "First, we examined ZBTB4 protein and mRNA expression in human normal pancreatic ductal epithelial cells (HPDE6-C7) and four pancreatic cancer cell lines (Bxpc-3, Panc-1, Aspc-1 and Cfpac-1)." (PMID 36949454, 2023). "The role of ZBTB4 in pancreatic cancer cells is not yet understood." (PMID 36949454, 2023). "Importantly, the lack of ZBTB4 expression in pancreatic cancer resulted in a poor prognosis." (PMID 36949454, 2023).
systemic juvenile idiopathic arthritis (1 paper, 2022). "Its suppression reduced proinflammatory cytokines production by regulating miR-150-5p/ZBTB4 axis via JAK/STAT signal pathway in systemic juvenile idiopathic arthritis." (PMID 35626352, 2022).
triple-negative breast carcinoma (1 paper, 2025). An invasive breast carcinoma which is negative for expression of estrogen receptor (ER), progesterone receptor (PR), and human epidermal growth factor receptor 2 (HER2). "On the other hand, overexpression of the demethylase FTO restrained the proliferation, invasion, and migration in triple-negative breast cancer cells via affecting the miR-17-5p/ZBTB4 axis." (PMID 40002690, 2025).
virus infection (1 paper, 2015). "In contrast, potential sumoylated forms of ZBTB4, ZBTB10 and ETV6 appeared to increase in abundance in the ICP0-null mutant infected samples, which may be related to the overall accumulation of sumoylated species that occurs during the mutant virus infection." (PMID 26200910, 2015).
cancer (18 papers, 2017 to 2026). A tumor composed of atypical neoplastic, often pleomorphic cells that invade other tissues. "ZBTB4 showed loss of expression in the majority of tumors and possessed the ability to predict cancer prognosis." (PMID 36949454, 2023). "The zinc-finger transcription factor ZBTB4 has been implicated in the initiation and progression of cancer, but its role in UC remains unknown." (PMID 42193937, 2026). "Furthermore, overexpression of ZBTB4 is associated with prolonged relapse-free survival of patients with cancers above." (PMID 36538280, 2023). "ZBTB4-deficient mice are susceptible to developing carcinogen-induced cancer." (PMID 31245293, 2019). "For the TCGA Pan-Cancer data, we analyzed the correlation between the abnormal expression of ZBTB4 and the survival of patients by Kaplan–Meier curves." (PMID 36949454, 2023). "Owing to a lack of comprehensive knowledge of ZBTB4, we used the TCGA pan-cancer database to reveal the differential expression of ZBTB4 in 26 human tumors." (PMID 36949454, 2023). "In conclusion, our pan-cancer analysis of ZBTB4 indicates the presence of aberrant expression of ZBTB4 in a variety of tumors." (PMID 36949454, 2023). "In this study, we found that ZBTB4 was highly correlated with immune infiltration of cancer in immune cell correlation analysis." (PMID 36949454, 2023). "We also investigated the correlation between the abnormal expression of ZBTB4 and the prognosis of cancer patients." (PMID 36949454, 2023). "The results indicated that ZBTB4 showed a significant positive correlation with most of the immune-related genes in the remaining cancers except for GBMLGG." (PMID 36949454, 2023). "First, based on the data obtained from The Cancer Genome Atlas, the overall survival of patients with high expression of ZBTB4 was longer than that of patients with low ZBTB4 expression." (PMID 34047477, 2021). "In, general, ZBTB4 usually acted as a transcription repressor, and was frequently downregulated in cancer." (PMID 31480180, 2020). "Among the multiple target genes of miR-106a in cancer cells, ZBTB4 is a transcriptional repressor regulating EZH2, a factor associated with decreased survival among BC patients." (PMID 29557526, 2018). "The pan-cancer genomic alteration landscape of ZBTB4 was investigated with the online tool." (PMID 36949454, 2023). "The results suggest that ZBTB4 may be involved in cancer progression and prognosis by interacting with the cancer microenvironment." (PMID 36949454, 2023). "This study reveals the important role of ZBTB4 in human pan-cancer." (PMID 36949454, 2023). "Data from TCGA pan-cancer were analyzed for ZBTB4 expression." (PMID 36949454, 2023). "Interestingly, quantities of Sp1, Sp3 and Sp4 were found to be suppressed in ZBTB4-overexpressing cancer cells." (PMID 36615262, 2022). "ZBTB4, a mammalian DNA-binding protein, was widely recognized as a transcriptional inhibitor and played an indispensable role in the genesis, development, and metastasis of cancer." (PMID 35774226, 2022). "Previous studies have also shown elevating m6A regulator METTL3 levels could increase the RNA modification of ZBTB4 and decrease levels of ZBTB4 mRNA, which in turn increase aneuploidy and genome instability across many frequent human cancers." (PMID 35003079, 2021). "ZBTB4 mainly serves as a transcriptional inhibitor in various cancer cells." (PMID 34047477, 2021). "Taken together, these studies indicate a tumor-suppressive role of ZBTB4 in cancer." (PMID 31245293, 2019). "Third, ZBTB38 paralogs, ZBTB4 and ZBTB33, regulate the expression of CDKN1 family genes in cancer cells." (PMID 30310057, 2018).